MYO1D (myosin ID)
Description:
Unconventional myosin that functions as actin-based motor protein with ATPase activity (By similarity). Plays a role in endosomal protein trafficking, and especially in the transfer of cargo proteins from early to recycling endosomes (By similarity). Required for normal planar cell polarity in ciliated tracheal cells, for normal rotational polarity of cilia, and for coordinated, unidirectional ciliary movement in the trachea. Required for normal, polarized cilia organization in brain ependymal epithelial cells (By similarity).
Synonyms: KIAA0727; myr4; PPP1R108
Tractability: Antibody: its Gene Ontology location is reachable by antibodies, with medium confidence. PROTAC: ubiquitination databases record sites on it; its protein half-life has been measured.
Gene: Protein-coding gene on chromosome 17 (32,492,522 to 32,877,192, reverse strand). Ensembl gene ENSG00000176658.
Subcellular location: Cytoplasm; Perikaryon; Cell projection, dendrite; Early endosome; Cytoplasm, cell cortex
Subcellular location (Human Protein Atlas): Cytosol
Gene Ontology:
Molecular function: protein binding; protein domain specific binding; actin filament binding; calcium-dependent protein binding; calmodulin binding; microfilament motor activity; ATP binding; cytoskeletal motor activity
Biological process: actin filament-based movement; cellular localization; endocytic recycling; endocytosis
Cellular component: extracellular exosome; actin cytoskeleton; apical dendrite; axolemma; axon; basolateral plasma membrane; brush border; cytoplasm; cytoplasmic vesicle; early endosome; endosome; microvillus; myelin sheath; myosin complex; neuron projection; neuronal cell body; perikaryon; plasma membrane; cell cortex; dendrite
Genetic constraint (gnomAD): Loss-of-function variants: 64 observed, 100.15 expected, observed/expected ratio (o/e) 0.64, 90% interval 0.52 to 0.79. The upper end of that interval is the gene's LOEUF score, 0.79, which puts it in group 3 of 6, group 1 being the genes least tolerant of losing a copy. Missense variants: 1,049 observed, 1,169.5 expected, observed/expected ratio (o/e) 0.9, 90% interval 0.85 to 0.94. Synonymous variants: 414 observed, 414.67 expected, observed/expected ratio (o/e) 1, 90% interval 0.92 to 1.08.
Homologues: Orthologues: chimpanzee MYO1D (99% identical), macaque MYO1D (99% identical), dog MYO1D (98% identical), guinea pig MYO1D (98% identical), mouse Myo1d (98% identical), pig MYO1D (98% identical), rat Myo1d (96% identical), rabbit MYO1D (94% identical), zebrafish myo1d (81% identical), tropical clawed frog myo1d (80% identical). Paralogues in human: MYO1G (61% identical), MYO1B (41% identical), MYO1C (41% identical), MYO1A (40% identical), MYO1H (40% identical), MYO7A (33% identical), MYO7B (32% identical), MYH7 (32% identical), MYH6 (31% identical), MYO5A (31% identical), MYH7B (31% identical), MYH10 (30% identical), and 32 more.
Diseases named in the same sentence as MYO1D in open-access papers:
MYO1D is named in the same sentence as 30 diseases in open-access papers, as found by Europe PMC text mining. Sharing a sentence is not in itself a finding about the gene and the disease. The quoted sentences say what the papers report.
autism (3 papers, 2011 to 2024). Persistent deficits in social interaction and communication and interaction as well as a markedly restricted repertoire of activity and interest as well as repetitive patterns of behavior. "Mutations in MYO1D have been linked to autism, confirming etiopathogenesis of this protein in neurodevelopmental as well as neurodegenerative disorders." (PMID 38674386, 2024). "The encoded protein, myogenic differentiation 1, is involved in myelin sheath formation and both common and rare variants have been associated with autism, supporting MYO1D’s role in neural development and functioning." (PMID 37794492, 2023).
breast carcinoma (3 papers, 2021 to 2024). "Overexpression of MYO1D has previously been associated with breast cancer cell motility and viability." (PMID 39322849, 2024). "The MDA-MB-231 and BT-549 breast cancer cell lines' vitality was assessed using the CCK-8 assay after MYO1D knockdown to examine the function of MYO1D." (PMID 38512527, 2024). "We examined MYO1D mRNA levels in several cell lines to clarify the function of MYO1D in breast cancer metastasis." (PMID 38512527, 2024). "Of the chosen gene signatures, MYO1D has been found to have increased expression levels in breast cancer and has the capacity to upregulate the expression of the Epidermal Growth Factor Receptor (EGFR), which improves the motility and viability of colorectal and breast cancer cells." (PMID 38512527, 2024). "Additionally, the expression of MYO1D was examined by immunohistochemistry staining in 30 pairs of breast cancer and 23 paratumor tissues." (PMID 38512527, 2024). "In vitro, MYO1D has been shown to facilitate the invasion and metastasis of breast cancer." (PMID 38512527, 2024). "In vitro experiments also confirmed that MYO1D facilitates breast cancer invasion and metastasis." (PMID 38512527, 2024). "Moreover, our results verified that MYO1D stimulates breast cancer invasion and metastasis." (PMID 38512527, 2024). "After knocking down MYO1D, the protein levels of N-cad and vimentin were reduced in MDA-MB-231 and BT-549 cells, which inhibited EMT (epithelial cell-to-mesenchymal transition) in breast cancer cells in comparison to the control group." (PMID 38512527, 2024).
prostate carcinoma (3 papers, 2017 to 2023). A carcinoma that arises from epithelial cells of the prostate gland. "Other genes found to be H3K27me3-enriched in prostate cancer tissues compared to normal tissues include MYO1D, TENM4, GRIN3B, all of which are involved in cell communication and cell adhesion." (PMID 28403887, 2017). "Myo1d is also overexpressed in prostate cancer, however, so far there is no direct evidence of the function of Myo1d on those cells." (PMID 34974807, 2022).
colitis (2 papers, 2018 to 2021). Inflammation of the colon. "The colitis phenotype in both pedigrees mapped to damaging Myo1d alleles using a recessive model of inheritance." (PMID 30279225, 2018). "Using forward genetics, we demonstrated that damaging mutations in the class I myosin MYO1D led to a defect that rendered mice susceptible to DSS-induced colitis." (PMID 30279225, 2018). "In this study, we report that MYO1D is necessary for the maintenance of intestinal homeostasis and provide an initial phenotypic characterization of the colitis phenotype caused by loss of MYO1D function." (PMID 30279225, 2018). "We found and validated mutations in Myo1d as a cause of increased susceptibility to DSS-induced colitis." (PMID 30279225, 2018). "Thus, impaired cell migration owing to disruption of actin cytoskeletal remodeling might also contribute to DSS-induced colitis susceptibility in Myo1d mutant mice." (PMID 30279225, 2018). "MYO1D is produced in the intestinal epithelium, and the colitis phenotype is dependent on the nonhematopoietic compartment of the mouse." (PMID 30279225, 2018).
Parkinson disease (2 papers, 2011 to 2024). A progressive degenerative disorder of the central nervous system characterized by loss of dopamine producing neurons in the substantia nigra and the presence of Lewy bodies in the substantia nigra and locus coeruleus. "MYO1D has been considered as a target for pharmacotherapy in Parkinson’s disease." (PMID 38674386, 2024).
autism spectrum disorder (1 paper, 2016). A spectrum of developmental disorders that includes autism, and Asperger syndrome. "In relation to disease, Myo1d has been identified as a candidate gene for participation in autism spectrum disorders." (PMID 27655972, 2016).
bone osteosarcoma (1 paper, 2022). A usually aggressive malignant bone-forming mesenchymal neoplasm arising from the bone. "Immunohistochemical staining showed the cytosolic localization of Myo1d protein in E11 cells, consistent with the previously reported localization of Myo1d protein in the human bone osteosarcoma cell line U-2 OS." (PMID 35736640, 2022).
Canavan disease (1 paper, 2016). A neurodegenerative disorder; its spectrum varies between severe forms with leukodystrophy, macrocephaly and severe developmental delay, and a very rare mild/juvenile form characterized by mild developmental delay. "Because Myo1d has been reported to interact with ASPA in vitro and colocalizes with ASPA in brain, Myo1d may also be related to Canavan disease, a fatal neurological disorder that results in the deterioration of myelin." (PMID 27655972, 2016).
hepatocellular carcinoma (1 paper, 2020). A malignant tumor that arises from hepatocytes. "miR-9 is frequently down-regulated in primary hepatocellular carcinoma and its restoration retards cell proliferation and migration by targeting IL-6, AP3B1, TC10, OC2, IGF2BP1, MYO1D, and ANXA241." (PMID 32393810, 2020).
Hypertension (1 paper, 2014). The presence of chronic increased pressure in the systemic arterial system. "MYO1D has been associated with hypertension, and phosphorylation of the myosin light chain, mediated by Ca+2, is necessary for the regulation of vascular small muscle contraction." (PMID 25519358, 2014).
leukemia (1 paper, 2023). A malignant (clonal) hematologic disorder, involving hematopoietic stem cells and characterized by the presence of primitive or atypical myeloid or lymphoid cells in the bone marrow and the blood. "The DNAm levels at three individual CG dinucleotides (CpG sites) in the genes MYO1D, STK17A, and SP140 correlated with CD34+ cell numbers in mobilized peripheral blood and with blast counts in leukemia." (PMID 37370186, 2023).
polysplenia syndrome (1 paper, 2021). "We discovered an extremely rare novel missense variant in MYO1D gene (Pro765Ser) presenting with visceral heterotaxy and left isomerism with polysplenia syndrome." (PMID 34589502, 2021). "In conclusion, we discovered missense mutation in MYO1D gene (c.2293C>T) in an Arab patient presenting with visceral heterotaxy and left isomerism with polysplenia syndrome by using higher-throughput WES technology." (PMID 34589502, 2021).
renal carcinoma (1 paper, 2023). A carcinoma arising from the epithelium of the renal parenchyma or the renal pelvis. "High levels of MYO1D have been described as a poor prognostic biomarker in urothelial cancer but as a good prognostic biomarker in renal cancer." (PMID 38203489, 2023).
triple-negative breast carcinoma (1 paper, 2024). An invasive breast carcinoma which is negative for expression of estrogen receptor (ER), progesterone receptor (PR), and human epidermal growth factor receptor 2 (HER2). "Our study is the first multiomic analysis to explore neutrophil-associated risk genes in triple-negative breast cancer and confirmed that high expression of MYO1D leads to a poor prognosis in TNBC." (PMID 38512527, 2024). "Compared to patients with non-triple-negative breast cancer, patients with triple-negative breast cancer had greater levels of MYO1D expression." (PMID 38512527, 2024).
tumor (6 papers, 2015 to 2024). "Mechanisms of tumor-promoting activities of MYO1D are linked to regulation of growth factor receptor trafficking." (PMID 33670106, 2021). "Mechanistically, SPAG6 promoted the translocation of MYO1D from the cytoplasm to the cell membrane, thereby activating the PI3K/AKT and ERK signaling pathways, which ultimately accelerating AML cell proliferation and tumor progression." (PMID 39508041, 2024).
cancer (3 papers, 2022 to 2025). A tumor composed of atypical neoplastic, often pleomorphic cells that invade other tissues. "MYO1D, a member of the myosin motor protein, controls cell movement and promotes the growth and invasion of cancer cells." (PMID 38283944, 2023). "And Myo1d contributes to colorectal carcinogenesis possibly as a novel oncogene and thus may serve as an additional target for suppression of RTK signaling in cancer treatment." (PMID 36347835, 2022).
neurodegenerative disease (1 paper, 2016). A disorder of the central nervous system characterized by gradual and progressive loss of neural tissue and neurologic function. "Thus, the role of Myo1d in myelination may be important in mental health and neurodegenerative disease." (PMID 27655972, 2016).
MYO1D also shares sentences with these, for which no sentence is quoted: acute myeloid leukemia (1 paper); Alzheimer disease (1); Angelman syndrome (1); bipolar disorder (1); colorectal cancer (1); diabetes (1); epilepsy (1); infection (1); neurodevelopmental disorder (1); neurological disorder (1); schizophrenia (1); Spitz nevi (1); spitzoid melanoma (1).